HIF1A (hypoxia inducible factor 1 subunit alpha)
Diseases named in the same sentence as HIF1A in open-access papers (continued):
Sharing a sentence is not in itself a finding about the gene and the disease.
renal fibrosis (continued). "In this study, the expressions of HIF-1α, Beclin1, autophagy-related genes 5-12 (Atg 5-12), and LC3 were significantly increased, and the expression of p62 was decreased in UUO-induced renal fibrosis." (PMID 33806080, 2021). "However, it remains a controversy whether HIF-1α promotes or antagonizes renal fibrosis." (PMID 34925478, 2021). "In this study, we show that QSG is capable of reducing HIF-1α levels in CRF patients, thereby limiting the progression of renal fibrosis." (PMID 31354858, 2019). "Regarding renal fibrosis and CKD, it is reasonable to anticipate that SUMO participates in this process via the TGF‐β and HIF‐1α signalling pathways." (PMID 30506859, 2019). "Although upregulation of HIF-1α has been shown to be protective in acute renal injury, increasing evidences suggest that continuous overactivation of HIF promotes progression of renal fibrosis." (PMID 30643536, 2018). "Previous studies have reported that RUNX1 interacts with HIF-1α and that HIF-1α promotes renal fibrosis via EMT." (PMID 29759484, 2018). "In both ischemia-reperfusion and ureteral obstruction induced renal fibrosis models, inactivation of endothelial HIF-2α, instead of HIF-1α, can result in enhanced inflammatory cell infiltration." (PMID 28468297, 2017). "DFO promotes HIF-1α activity, and HIF-1α activation exacerbates UUO-induced renal fibrosis via the EMT." (PMID 24586712, 2014). "Additionally, studies report that HIF-1α mediates myeloid macrophage polarization via PFKFB3 and promotes renal fibrosis." (PMID 41375167, 2025). "Here, we offered more proof that acrolein scavengers may be able to partially restore PKM2 function, prevent HIF1α accumulation, halt EMT and finally lower the expression of renal fibrosis markers." (PMID 37007793, 2023). "A mutual regulatory relationship between HIF-1α and TGF-β1 promotes renal fibrosis." (PMID 35957825, 2022). "Unfortunately, there is a lack of in-depth research on how HIF-1α regulates GLUT1 to affect energy metabolism in renal fibrosis." (PMID 35957825, 2022). "We specifically addressed certain signaling pathways (Rho/ROCK, hypoxia-inducible factor-1α [HIF-1α], and transforming growth factor-β1 [TGF-β1]), and α-smooth muscle actin (α-SMA) expression, all of which influence renal hypoxia, renal fibrosis, and renal function." (PMID 35784704, 2022). "In reverse, HIF‐1α mediates TGF‐β1 gene expression, which may result in a feedback loop and promote the formation of renal fibrosis and injury." (PMID 35441828, 2022). "Hif-1α has also been reported to have crosstalk with several pathways that promote fibrosis, such as Notch, PI3K/Akt, and Smad3 pathways during the process of renal fibrosis." (PMID 36675720, 2022). "It was also apparent that fasudil may increase RBF, combat medullary hypoxia, and limit renal fibrosis through various signaling pathways (Rho/ROCK, HIF-1α, and TGF-β1) and expression of α-SMA." (PMID 35784704, 2022). "Similarly, many studies are focusing on targets of renal fibrosis, such as TGF-β, p38MAPK, and HIF-1α." (PMID 35855831, 2022). "Recent studies have proven that Notch could be activated by HIF-1α, and our previous study demonstrated that increased HIF-α in endothelial cells accelerated renal fibrosis through Notch activating." (PMID 34268320, 2021). "Several previously reported protective genes (hypoxia inducible factor 1, HIF-1α; heme oxygenase 1; HO-1, colony-stimulating factor 2, CSF-2; bone morphogenetic protein-7, BMP-7; and activin-like kinase 3; ALK3) against renal fibrosis progression after ischemia reperfusion were evaluated after IR." (PMID 34302012, 2021). "Although HIF-1α was found to be involved in fibrosis, the relationship among miR-21, PPARα and HIF-1α in aging-related renal fibrosis has not been reported." (PMID 32963130, 2020). "ATP1B1 and HIF-1α are also important in the processes of EMT and renal fibrosis." (PMID 29759484, 2018).
renal fibrosis (continued). "HIF-1α, TGF-β1, and VEGF have been identified as the key regulators of renal fibrosis in DN." (PMID 30420600, 2018). "The HIF-1α level was higher in cells cultured in hypoxia than in those cultured in normoxia; studies have shown that increased HIF-1α plays an important role in aggravating renal fibrosis." (PMID 29462885, 2018). "In contrast, renal fibrosis was not affected by the global reduction of Hif1α, at least not in the early phase of diabetic exposure." (PMID 28774305, 2017). "In our system, the abrogation of HIF-1α expression could promote proximal epithelial cell dysfunction and EMT process contributing to renal fibrosis." (PMID 28106131, 2017). "In conclusion, our present study indicated that transplanted hAFSCs could alleviate the progression of renal fibrosis by elevating VEGF protein levels, increasing PTC density and decreasing the expression of HIF-1α and TGF-β1." (PMID 23724119, 2013). "Thus, therapeutic strategies targeting HIF1α- and BNIP3-mediated mitophagy may alleviate renal fibrosis and delay the progression of CKD." (PMID 36928344, 2023). "Unfortunately, there are no reports on the effect of HIF-1α on OXPHOS in renal fibrosis." (PMID 35957825, 2022). "Numerous studies have demonstrated that HIF, particularly HIF-1α, is a key regulator of renal interstitial fibrosis in the progression of CKD, though controversial opinions may exist on whether it promotes or suppresses renal fibrosis." (PMID 33430279, 2021). "Finally, our findings suggest that NE-THCQ may inhibit renal fibrosis progression mainly by regulating the inflammatory process, reversing EMT and decreasing ECM deposition through PI3K/AKT/mTOR and HIF-1α/VEGF signaling pathways." (PMID 32372953, 2020). "Notably, following ANGPTL4 knockdown, the level of α-SMA remained greater than that in the control group, indicating that ANGPTL4 may not be the sole regulatory factor in renal fibrosis and that other HIF-1α-mediated regulatory pathways, such as the PI3K/AKT signaling pathway, may also be involved." (PMID 38992710, 2024).
pulmonary hypertension (99 papers, 2010 to 2026). Increased pressure within the pulmonary circulation due to lung or heart disorder. "Mitochondrial reactive oxygen species (mtROS) have been implicated in the development of chronic hypoxia-induced pulmonary hypertension (PH), potentially through hypoxia-inducible factor-1α (HIF-1α) stabilization." (PMID 41810557, 2026). "In parallel, HIF-1α activity in both endothelial and smooth muscle cells has been shown to be implicated in the pathogenesis of hypoxia-induced pulmonary hypertension." (PMID 40722943, 2025). "Under hypoxic conditions, HIF-1α plays a key role in extensive vascular remodeling, ultimately leading to the occurrence of pulmonary hypertension, which is one of the important causes of death in SSc patients." (PMID 35733188, 2022). "Using a model of pulmonary hypertension associated with pulmonary fibrosis, our group has recently demonstrated that mice with BMPRII mutation expressed a high amount of HIF1α in the lung, corresponding with worsening pulmonary hypertension." (PMID 27446973, 2016). "Studies of mice partially deficient for HIF-1α showed delayed development of pulmonary vascular remodeling, pulmonary hypertension, and right ventricular hypertrophy, suggesting an important role of HIF-1α in the development of vascular remodeling." (PMID 23902684, 2013). "Given that higher basal levels of HIF-1α protein were observed in female human pulmonary artery smooth muscle cells, which increases the risk of females developing pulmonary arterial hypertension, we examined the sex difference of HIF-α activity in the intestine in HIF-α reporter mice." (PMID 39585307, 2024). "The key pathogenic features of pulmonary hypertension are endothelial apoptosis and vascular inflammation, which are caused by the down-regulation of Amphiregulin, accompanied by HIF-1a and BAD-mediated up-regulation of the target genes such as RRP1B, PHB2, and NCOA6." (PMID 35732465, 2022). "Under hypoxia, increased HIF1α causes decreased expression of PPARγ, which increases proliferation of distal pulmonary arterial smooth muscle cells and promotes vascular remodeling, resulting in pulmonary hypertension." (PMID 33928137, 2021). "Pulmonary hypertension (PH) can be caused by hypoxia or conditions mimicking hypoxia by high NO production leading to inhibition of mitochondrial electron transport and induction of Hif1α (hypoxia‐inducible factor α)." (PMID 31538680, 2020). "Additionally, air-breathing rats fed an iron-restricted diet rapidly develop pulmonary arterial hypertension and right ventricular hypertrophy, in association with increased lung expression of HIF-1α and HIF-2α." (PMID 27140401, 2016). "Nuclear YBX1 acts as a transcription factor, directly activating HIF‐1α transcription in pathological pulmonary hypertension." (PMID 41482854, 2026). "Our single-center retrospective cohort study was limited by the absence of large-scale, multicenter data to further validate and compare serum VEGF and HIF-1α levels in patients with other forms of pulmonary hypertension." (PMID 39948088, 2025). "In this context, mice with heterozygous germline deletion of HIF-1α or HIF-2α exhibit attenuated development of pulmonary hypertension upon chronic hypoxic exposure." (PMID 40722943, 2025). "HIF-1α, an important factor in the progression of pulmonary arterial hypertension, can exacerbate endoplasmic reticulum stress, while endoplasmic reticulum stress can in turn stabilize HIF-1α, forming a pathogenic feedback loop." (PMID 41268527, 2025). "Another mechanism of pulmonary hypertension is the uninhibited and upregulated HIF-1α pathway during hypoxia in patients receiving treatment with belzutifan." (PMID 40806229, 2025).
pulmonary hypertension (continued). "Previous studies in our laboratory have shown that Calpain-1 mediates vascular remodeling and fibrosis with hypoxia pulmonary hypertension through HIF-1α." (PMID 38878112, 2024). "According to previous research results in our laboratory, Calpain-1 mediates vascular remodeling and fibrosis through HIF-1α in hypoxia pulmonary arterial hypertension." (PMID 38878112, 2024). "HIMF-promoted pulmonary hypertension was markedly reduced in HIF-1α (+/−) mice and was driven by the activation of a dysregulated vascular endothelial growth factor receptor 2-A-vascular endothelial growth factor pathway." (PMID 36984870, 2023). "In the mouse model, the degree of HIMF-induced pulmonary vascular remodeling and the development of pulmonary hypertension, both in wild-type (HIF-1α (+/+) and HIF-1α null heterozygous (HIF-1α (+/−), has been studied." (PMID 36984870, 2023). "The normoxic activation of HIF-1α by cobalt chloride leads to pulmonary hypertension in vivo and in PASMC, and increases fission, fragmenting the mitochondrial network." (PMID 36819102, 2023). "Experimental and clinical data suggest that HIF-1α activation exacerbates the progression of pulmonary hypertension." (PMID 36142307, 2022). "HIF-1α was activated in vitro in human pulmonary artery smooth muscle cells, demonstrating a role of HIF-1α in pulmonary hypertension pathogenesis." (PMID 35634337, 2022). "It is confirmed that HIF-1α activation is involved in vascular remodeling in pulmonary hypertension." (PMID 35479305, 2022). "Taken together, these results imply that hypoxia up‐regulates Cx43 in a HIF‐1α‐dependent manner and then promotes the proliferation and migration of PASMCs, which subsequently leads to hypoxic pulmonary vasoconstriction and pulmonary hypertension." (PMID 34698450, 2021). "Chronic hypoxia-induced pulmonary hypertension was significantly attenuated or delayed in mice hemizygous for either HIF1α or HIF2α and in mice with vascular smooth muscle HIF1α, endothelial, or global partial HIF2α deletion." (PMID 33578749, 2021). "It is downregulated in mouse and rat models of pulmonary hypertension by a HIF1α-dependent mechanism." (PMID 34068984, 2021). "Pulmonary arterial hypertension is accompanied by reduced MFN2 and excessive DRP1 caused by increased hypoxia inducible factor 1 alpha (HIF-1α) activation and decreased PGC-1α activity." (PMID 34938787, 2021). "During the development of pulmonary hypertension and heart failure, HIF-1α-induced vascular remodeling also plays an important role." (PMID 32760290, 2020). "This outcome indicated that HIF-1α is a vital downstream regulator in the process of HIMF-induced pulmonary hypertension, which means HIF-1α plays an important part in PH development." (PMID 32760290, 2020). "HIF-1α is known to contribute to the pathology of pulmonary hypertension, with some work specifically interrogating endothelial HIF signaling." (PMID 33178179, 2020). "Nevertheless, our findings clearly demonstrated that the myeloid cells‐specific deletion of HIF‐1α suppressed hypoxia‐induced pulmonary hypertension and myeloid cells played important roles in the progression of pulmonary arterial remodeling." (PMID 30927327, 2019). "Our findings suggest that HIF‐1α in myeloid lineage cells is involved in the development of hypoxia‐induced pulmonary hypertension." (PMID 30927327, 2019). "We generated myeloid‐specific HIF‐1α knockout (MyeHIF1KO) mice by using Cre‐lox P system, and exposed them to hypoxic conditions for 3 weeks to induce pulmonary hypertension." (PMID 30927327, 2019). "Previous studies in adult pulmonary hypertension reported that increased hypoxia‐inducible factor–1α (HIF‐1α) signaling contributes to pulmonary vascular remodeling." (PMID 30706701, 2019). "In pulmonary arterial hypertension, increased HIF1A promotes DRP1-driven mitochondrial fission and fragmentation in human lung and pulmonary arterial smooth muscle cells, while decreasing MFN2 activity." (PMID 29463805, 2018).
pulmonary hypertension (continued). "In their study, a rodent model of pulmonary hypertension with activation of HIF1α had inhibited expression of voltage-gated channel, KV1.5." (PMID 27446973, 2016). "Tamoxifen-induced silencing of smooth muscle HIF-1α expression attenuates pulmonary vascular remodeling and pulmonary hypertension in chronically hypoxic mice, suggesting a central role for HIF-1α in the pulmonary vascular response to hypoxia." (PMID 25814954, 2015). "HIF-1α is involved in the response to hypoxia through oxygen homeostasis and also in myocardial, brain and retinal ischemia, pulmonary hypertension, preeclampsia, intrauterine growth, retardation and cancer." (PMID 25695729, 2015). "miR-206 has exhibited its regulation of fibroblast growth factor, Hmgb3 and HIF-1α/Fhl-1 pathways in amyotrophic lateral sclerosis, muscle regeneration and pulmonary hypertension, respectively." (PMID 25816284, 2015). "In cultured hypoxic pulmonary artery smooth muscle cells (PASMCs), miR-206 promotes the Hypoxia-induced pulmonary hypertension though the HIF-1a/Fhl-1 pathway." (PMID 24887070, 2014). "Mice with heterozygous deficiency for functional HIF genes, either HIF-1α or HIF-2α, developed less polycythemia and pulmonary hypertension in response to hypoxia." (PMID 24201705, 2014). "HIF-1α controls a large program of genes critical to the development of pulmonary arterial hypertension." (PMID 21819559, 2011). "Our results are in line with a previous report confirming that hypoxic pulmonary hypertension injury could be aggravated by activating the TRAF6/NF-κB/HIF-1α pathway." (PMID 40666114, 2025). "CNP/cGMP signaling counteracts metabolic reprogramming in pulmonary arterial hypertension pericytes by reducing HIF1α, GLUT-1, and CAD activity, thereby normalizing glycolysis and pyrimidine synthesis and limiting hyperproliferation, highlighting its therapeutic potential." (PMID 40796654, 2025). "In recent years, many studies have confirmed that HIF-1α is closely related to the occurrence and development of inflammation and plays a strong pro-inflammatory role in the pathogenesis of rheumatoid arthritis, psoriasis, pulmonary hypertension, and tumors." (PMID 37007020, 2023). "Although LC3B is usually associated with a role in the autophagic pathway, previous studies have described several additional alternative functions, including a protective role in the development of hypoxia-induced pulmonary hypertension (PH) via the HIF-1α pathway." (PMID 36881560, 2023). "miRNA-338 could modulate pulmonary-hypertension-associated endothelial dysfunction with implications for pulmonary vascular and respiratory function through directly binding to the 3′-UTR of the HIF-1α mRNA, which causes abnormal ET-1 expression." (PMID 36142307, 2022). "HIF1A was reported to play a vital role in hypoxia-induced pulmonary hypertension." (PMID 35859795, 2022). "This may be of importance in the context of pulmonary hypertension given the known role of HIF-1α in pulmonary hypertension but to date this action of XIST has only been reported in colonic cancer cells." (PMID 34068984, 2021). "Both HIF1α and HIF2α isoforms have been extensively studied in pulmonary hypertension (PH)." (PMID 32972983, 2021). "The intervention in HIF‐1α pathway may be a novel strategy for the treatment of pulmonary hypertension." (PMID 30927327, 2019). "Integration of abnormalities in the mitochondria activates downstream effectors, such as HIF-1α, which is induced at both transcriptional and protein levels in PASMCs and pulmonary arterial endothelial cells obtained from patients with pulmonary hypertension and animal models." (PMID 31083380, 2019). "However, we were unable to determine the most important gene regulated by HIF‐1α that is involved in the development of pulmonary hypertension, which we acknowledge as another limitation of this study." (PMID 30927327, 2019).